SHH (sonic hedgehog signaling molecule)
Diseases named in the same sentence as SHH in open-access papers (continued):
Sharing a sentence is not in itself a finding about the gene and the disease.
medulloblastoma (continued). "At the same time, the field of embryonic tumors was also full of key publications with the identification of recurrent alterations in medulloblastomas, allowing classification into three groups based on the activation of two major molecular pathways: WNT and Sonic Hedgehog (SHH)." (PMID 39135755, 2024). "The two subgroups, Group 3 and Group 4 medulloblastomas, collectively known as non-WNT/non-SHH, lack specific subgroup-defining mutations but exhibit distinct clinical and biological features." (PMID 39518048, 2024). "Here, the authors find that SHH-inactivation of p38 results in stabilization of the transcription factor GLI1 via dephosphorylation at Ser937, resulting in expression of SHH genes and presenting a potential therapy strategy for medulloblastoma and BCC." (PMID 38307877, 2024). "Since the adoption of the molecular-based classification of medulloblastoma into wingless (WNT) activated, sonic hedgehog (SHH) activated, group 3, and group 4, research efforts have been directed towards unraveling the genetic, epigenetic, transcriptomic, and proteomic profiles of each subtype." (PMID 37568705, 2023). "Compared with other tumor and normal cells, the ecDNA+ cell cluster also overexpressed GLI2 (q < 0.001), a mediator of SHH-mediated transcription and marker for SHH medulloblastoma, despite GLI2 not being affected by copy number alteration in this tumor." (PMID 37945900, 2023). "In addition, compared to SHH medulloblastomas, CAL SHH ATRT also showed the overexpression of genes involved in NOTCH, WNT, and FGF signaling pathways and the overexpression of stem cell and neuronal progenitor genes markers." (PMID 37863903, 2023). "Based on gene expression and DNA methylome profiles, medulloblastomas are nowadays classified into four molecular groups, namely Wingless (WNT), Sonic Hedgehog (SHH), Group 3 (G3), and Group 4 (G4), with each group being associated with specific genetic alterations and activated signaling pathways." (PMID 37976029, 2023). "In specific, mebendazole was also found to inhibit SHH signaling by hindering the formation of the primary cilium, and thus resulted in decreased proliferation of DAOY cells in vitro and extended the survival of SHH medulloblastoma orthotopic models." (PMID 37568705, 2023). "Around 2010, several researchers reported that medulloblastomas comprise at least four distinct molecular subgroups: wingless signaling activated (WNT), Sonic-hedgehog signaling activated (SHH), Group 3, and Group 4, largely based on transcriptome profiles and a few known genetic alterations." (PMID 37296767, 2023). "WNT-activated and non-WNT/non-SHH-activated medulloblastomas are underrepresented in adults; this makes prognostication research in these subgroups challenging." (PMID 36920679, 2023). "Medulloblastoma is composed of four distinct molecular and clinical variants: WNT, Sonic Hedgehog (SHH), group 3, and group 4 (often termed non-WNT, non-SHH)." (PMID 38132264, 2023). "Furthermore, it is worth noting that the SHH and WNT subgroups have better prognosis and outcomes than the other two Medulloblastoma subgroups suggesting that the presence of primary cilia in these tumors results in a less malignant phenotype." (PMID 35295905, 2022). "Medulloblastoma (MB) was classified into four molecular subgroups: WNT, SHH, group 3, and group 4." (PMID 36358838, 2022).
medulloblastoma (continued). "The sonic hedgehog (SHH) pathway is a highly conserved developmental signaling pathway that is activated in many human cancers, including basal cell carcinoma (BCC), acute myeloid leukemia (AML), and medulloblastoma." (PMID 36688010, 2022). "Upon long-term treatment with LDE225, the RNA levels of the known SHH pathway genes Ptch1, Smo, Gli1, and Gli2 were equivalent to those in control-treated tumors in SD-CSC medulloblastomas, indicating continued activation of the SHH pathway consistent with acquired mutations in this pathway." (PMID 36688010, 2022). "Medulloblastoma contains multiple molecular subtypes, and the most recent molecular typing studies currently classify medulloblastoma into four broad subtypes, namely, WNT, SHH, group 3, and group 4." (PMID 35866054, 2022). "The outcome varies in SHH-activated medulloblastoma and although metastasis is not common, if a patient has a metastatic tumor, the outcome is usually worse." (PMID 33869004, 2021). "Unlike WNT- and SHH-activated medulloblastoma, the Group 3 tumors are less defined; some studies showed MYC amplification leading to tumor formation in this subgroup." (PMID 33869004, 2021). "We also examined SHH-subgroup tumors stratified by age, irrespective of subtype; infant medulloblastomas showed significantly higher HLA-DRA, consistent with developmental differences producing differences in the TME, as in our model." (PMID 34021242, 2021). "Medulloblastomas, malignant embryonal tumors (grade 4) relatively common in the pediatric population and arising in the posterior fossa, also acknowledge new molecular subtypes, depending on WNT- and Sonic Hedgehog (SHH-)status." (PMID 33498680, 2021). "Similarly, in medulloblastoma, analysis of the well-defined WNT and SHH subgroups identified seven candidate SSV genes in each." (PMID 34230614, 2021). "Unlike the SHH-activated subtype of medulloblastoma, the WNT-activated subtype confers the best prognosis, although it is also the least commonly occurring variant." (PMID 34012965, 2021). "In 2012, it was agreed during an international meeting that medulloblastoma has four distinctive molecular subgroups named: Wingless (WNT-good prognosis), Sonic Hedgehog (SHH-intermedia prognosis), Group 3 (Grp3-bad prognosis) and Group 4 (Grp4-intermedia prognosis)." (PMID 34944941, 2021). "Gorlin syndrome should be considered in young children with SHH activated medulloblastoma, especially DMB and MBEN but cannot be ruled out for CMB." (PMID 34888241, 2021). "In the last decade, the clinical and biological heterogeneity of medulloblastoma has been evaluated in terms of transcriptional and methylation profile with the definition of four distinct molecular subgroups: WNT, Sonic Hedgehog (SHH), group 3, and group 4." (PMID 32899294, 2020). "Efforts to dissect the molecular underpinnings of medulloblastoma have identified four main subgroups - WNT, Sonic hedgehog (SHH), Group 3 and Group 4 - with distinct transcriptional, DNA methylation and mutational profiles, and different clinical characteristics and outcomes." (PMID 31924815, 2020). "In a study aimed at identifying novel putative therapeutic targets for SHH-dependent medulloblastomas, CK2 was found as a SHH signaling driver, and its inhibition was shown to decrease the viability of patient-derived cells resistant to SHH inhibitors, in vitro and in murine models." (PMID 31277672, 2019). "Having shown that the expression of CD24 is significant in our murine model we sought to ascertain its relevance in human medulloblastoma and its four subgroups: WNT, SHH, Group 3 and Group 4, whose stratification is based on tumour location and genetic inception." (PMID 30657775, 2019). "GRK2 can regulate SHH/SMO signaling at different points along their signaling pathway and is expressed in medulloblastomas, but to date, has not been implicated in medulloblastoma biology." (PMID 31554835, 2019).
medulloblastoma (continued). "Historically identified on a histopathological basis, medulloblastoma was later classified into four major subgroups—namely WNT, SHH, Group 3, and Group 4—each characterized by distinct transcriptional profiles, copy-number aberrations, somatic mutations, and clinical outcomes." (PMID 30923703, 2019). "In the SHH-induced mouse model of medulloblastoma, highly expressed nonreceptor tyrosine kinase HCK phosphorylates GLI1, resulting in enhancement of GLI1-mediated target gene activation." (PMID 30675521, 2019). "These novel findings add to our understanding of the downstream activity of the SHH pathway and may help bridge the gap between the downstream effector YAP1 and the unregulated proliferation in SHH medulloblastoma." (PMID 31541170, 2019). "SHH medulloblastoma is characterized by aberrations in the SHH pathway, so our next question was to determine whether HELLS is upregulated in an SHH medulloblastoma mouse model." (PMID 31541170, 2019). "The current update of the WHO classification of tumors of the central nervous system distinguishes within medulloblastomas four molecular subgroups that have a prognostic and therapeutic value: WNT-activated, SHH-activated and enigmatic group 3 and group 4 also described as the non-WNT/non-SHH." (PMID 29547527, 2018). "Genomics applied to medulloblastoma defined four medulloblastoma subgroups, each characterized by a distinct molecular/genetic signature, distinct patient demographics, and a distinct clinical profile (WNT, Sonic Hedgehog or SHH, Groups #3 and #4)." (PMID 30360486, 2018). "SHH activation in a spectrum of early and late GNPs generated the development of medulloblastomas, but not other types of brain tumors." (PMID 30279357, 2018). "Similarly, in medulloblastoma, the role of AMPK as both an inhibitor of GLI1 and SHH signaling (tumor-suppressive effect) as well as a promoter of CNBP and polyamine metabolism (pro-tumorigenic effect) supposes a dual role for AMPK in this disease context." (PMID 30360486, 2018). "Medulloblastoma, the most common malignant pediatric brain tumor, is a heterogeneous disease, with the existence of at least four molecular types: Wingless (WNT), Sonic Hedgehog (SHH), Group 3 and Group 4 tumors." (PMID 29427151, 2018). "Taken together with the complementary report that both SHH and Group #3 medulloblastomas show a high level of expression of CNBP and ODC1 proteins, the SHH/AMPK/CNBP axis could then have a critical role in both the SHH and Group #3 subgroups." (PMID 30360486, 2018). "Medulloblastoma, an embryonal tumor of the posterior fossa and the most frequent malignant brain tumor of children, is classified into four molecular subtypes: Wingless (WNT), Sonic Hedgehog (SHH), Groups 3 and 4 subtypes." (PMID 30279357, 2018). "According to several reports, medulloblastoma is classified into four molecularly distinct subgroups –WNT, SHH, Group C (MYC activated), and Group D. Zebrafish tumors induced by rb1 somatic inactivation displayed an apparent up-regulation of genes in neural development and NOTCH pathway." (PMID 28903419, 2017). "The collaboration of SHH and MYCN may be pivotal in both medulloblastoma and basal cell carcinoma regulation, and further insights are necessary for the identification of potential novel therapeutics." (PMID 28358317, 2017). "Thus, we further analyzed pathway signatures of DEGs and focused especially on neurogenesis, WNT, SHH, and NOTCH pathways which are used as subgroup classifications of human medulloblastoma." (PMID 28903419, 2017). "The fourth genetically defined entity represents the majority of medulloblastomas lacking either WNT or SHH pathway activation (non-WNT/non-SHH medulloblastomas)." (PMID 27781424, 2016).
medulloblastoma (continued). "Metadata analysis of microarray data from 437 human medulloblastoma samples establishes that SERPINE2/PN-1 is expressed by the vast majority of all medulloblastomas, with levels highest in the WNT and SHH subgroups." (PMID 25901736, 2015). "More recent classifications, which divide medulloblastomas into four molecular subgroups [WNT, Sonic Hedgehog (SHH), Group 3 and Group 4] show that tumors with genomic alterations in SHH and WNT signaling pathways overall had better prognosis than Groups 3 and 4 medulloblastomas." (PMID 26380221, 2015). "Recent progress in the molecular stratification of medulloblastoma has revealed striking heterogeneity that has led to stratification into several genetically distinct clinical subgroups (WNT, SHH, Group 3, Group 4) which respond differently to current therapies." (PMID 25539912, 2014). "WNT and SHH signalling regulate NSC self-renewal and differentiation, and deregulation of these pathways is consistent with mouse models implicating a NSC cell of origin for at least some WNT and SHH subgroup medulloblastoma." (PMID 25412507, 2014). "For SHH and WNT medulloblastoma, gene expression profiles overlap with stem cell regulatory pathways while activated expression of later neuronal signaling and maintenance pathway genes, is characteristic of Group 3 and Group 4 medulloblastoma." (PMID 25412507, 2014). "A lack of YAP1 immunoreactivity in medulloblastoma tumors is indicative of the Non-WNT/SHH subgroup (encompassing both Groups 3 and 4)." (PMID 24252460, 2013). "For instance, the observation that medulloblastomas with chromosome 17 aberrations have an adverse outcome is due to the fact that they are most frequent in Group 3 and Group 4 medulloblastomas, which fare worse than the WNT and SHH subgroups." (PMID 22358457, 2012). "This interpretation is supported by epidemiological data that suggests SHH-driven medulloblastoma do not occur at different rates in prepubertal boys and girls." (PMID 22277186, 2012). "Unlike SHH-subtype medulloblastomas, WNT-subtype medulloblastomas actually arise within the dorsal brainstem and not in the cerebellum proper." (PMID 21427785, 2011). "A second subtype, not completely separated from all other medulloblastomas in their cluster analyses, was found to be enriched in mutations in either PTCH1 or SUFU and was characterized by activation of the SHH signaling pathway." (PMID 18769486, 2008). "We found frequent mono-allelic expression in G3 and G4, but neither SHH nor WNT medulloblastomas." (PMID 39753768, 2025). "The increase in CD4 T cells predicts a better prognosis in medulloblastoma patients, particularly within the SHH and non-WNT/non-SHH subgroups, and they might be taken as a therapeutic target for medulloblastoma." (PMID 40575173, 2025). "Our findings demonstrate that developmental mechanisms in cerebellar organoids reflect in vivo processes of regionalisation and SHH signalling, and offer new insights into early pathophysiological events of medulloblastoma tumorigenesis without the use of animal models." (PMID 38411252, 2024). "Medulloblastoma (MB) has been extensively analyzed in genomic, transcriptomic, and methylation studies classifying MB into molecular subgroups—Wingless (WNT), sonic hedgehog (SHH), Group 3, and Group 4—by clinically relevant and unique transcriptional, genomic, and epigenetic features." (PMID 34351088, 2022). "In addition, WNT-activated medulloblastomas often have classical morphology, and the large cell/anaplastic medulloblastomas are included in either the SHH-activated group or non-WNT/nonSHH group." (PMID 35969220, 2022). "Thus, beyond SHH inhibition, no other targeted therapy is currently being used upfront or at relapse in children with medulloblastoma." (PMID 35053536, 2022).
medulloblastoma (continued). "However, as cell line models are not available for WNT medulloblastoma, we focused on functional validation of the SHH candidates." (PMID 34230614, 2021). "Targeting other key pathways together with SHH signaling is a potential strategy, as there is considerable heterogeneity among SHH subgroup MB, suggesting that non-transcriptional mechanisms are also involved in SHH-signaling-mediated tumorigenesis in medulloblastoma." (PMID 34436033, 2021). "The importance of Olig2+ medulloblastoma stem cells was shown in prior studies where targeting the Olig2+ population, either by conditional ablation of Olig2-expressing cells using HSV TK or conditional genetic deletion of the Olig2 locus, reduced the growth of SHH-driven medulloblastomas in mice." (PMID 34021242, 2021). "Non-WNT/SHH-activated medulloblastomas are less well characterized in terms of pathway activation." (PMID 32758285, 2020). "For example, among the newly described non-WNT- and non-SHH-driven medulloblastoma subgroups, ~40% of patients harboring MYC amplifications may be candidates for immune checkpoint inhibition." (PMID 32676456, 2020). "While the WNT and SHH subgroup can be clearly identified based on the WNT and SHH signaling pathway mutations, much less is known about Group 3 and Group 4 tumors, and these subgroups remain as non-SHH/non-WNT medulloblastomas in WHO’s 2016 classification for diagnostic considerations." (PMID 32508873, 2020). "However, there was no clustering of the medulloblastoma subgroups SHH, WNT, group 3 and group 4 based on YBX1 expression." (PMID 32585856, 2020). "To functionally validate the activation of the SHH pathway, we confirmed the upregulation of the transcription factor GLI1, a main target gene of the pathway, in ITD-positive samples compared to the normal brain and a medulloblastoma of the WNT subtype by qRT-PCR." (PMID 27825128, 2016). "In medulloblastoma cells, CUR was able to arrest cells at the G2/M phase of the cell cycle and induce apoptosis by down-regulating the expression of the sonic hedgehog homolog (SHH) protein and its downstream molecules GLI1 and protein patched homolog 1 (PTCH1)." (PMID 25918934, 2015). "However, a Mycn but not c-Myc conditional knockout can prevent Sonic hedgehog (SHH) induced medulloblastoma precursor cell proliferation in vitro and medulloblastoma formation in vivo." (PMID 26673823, 2015). "Although our in vivo model resembles group 3 medulloblastoma, we assume based on our in vitro findings and the common feature of medulloblastoma to express MKI targets, that SHH-, WNT- and group 4 medulloblastoma might also benefit from Pazopanib and Sorafenib treatment." (PMID 25216529, 2014). "In addition, CD200 mRNA levels were significantly elevated in the group 4 (sonic hedgehog/cMYC negative) medulloblastoma subset compared to sonic hedgehog positive (SHH+) and group 3 (cMYC+) subsets (p = 0.001 and p = 0.001 respectively)." (PMID 25598973, 2014). "Molecularly, medulloblastoma has been classified into four subtypes based on global gene expression profiling and DNA copy number analyses; these include tumors with aberrant regulation in the WNT and Sonic Hedgehog (SHH) pathways as well as two other less defined Group 3 and Group 4 tumors." (PMID 24970811, 2014). "ADORA1 was under-expressed in the Non-WNT/SHH group (0.088-fold, p = 0.03), again suggesting that loss of ADORA1 activity may play a role in the pathogenesis of a Non-WNT/SHH medulloblastoma tumors, especially those seen in Cluster “E”." (PMID 24252460, 2013). "It has been noticed that the curcumin-resistant medulloblastoma cells, which exhibited no decrease in the levels of SHH and Bcl-2 levels could be sensitized to curcumin by a co-treatment with SMO antagonist, cyclopamine." (PMID 21859497, 2011).